IL6 (interleukin 6)
Diseases named in the same sentence as IL6 in open-access papers (continued):
Sharing a sentence is not in itself a finding about the gene and the disease.
tumor (continued). "In addition, after anti-IL-6 treatment and cryo-thermal therapy, a higher percentage of Tfh was observed compared to the tumor-bearing control group, while combination therapy significantly reduced it to the lowest level among the four groups." (PMID 37108179, 2023). "Tumor sphere numbers and sizes increased in IL-6-induced environment." (PMID 37987305, 2023). "In addition, recent study found that TAMs can promote tumor growth through producing IL-6, but accounting for majority of CD1d-expressing cells." (PMID 36845095, 2023). "Il6 and Ccl2 showed a disparate behavior to acidosis in the two different tumor cell lines studied." (PMID 38069241, 2023). "Moreover, GSEA was conducted and found that there was a dynamic correlation between high COL5A2 expression and hallmarks of tumor such as “angiogenesis”, “IL6-JAK-STAT3 signaling” and “NOTCH signaling”." (PMID 37723519, 2023). "Researchers found that individuals with NSCLC with a low baseline concentration of IL-6 in plasma specimens or tumor tissues could derive greater benefit from ICIs." (PMID 37833968, 2023). "However, increasing evidence supports that IL-6 trans-signaling is a key player in anti-tumor T cell responses." (PMID 36875137, 2023). "This contrasts with studies on HNSCC cell lines, which found that irradiation (2, 5 and 10 Gy) stimulated the release of IL6 within 24 h post-irradiation from fibroblasts, which will be present in the tumour biopsy samples, as well as reducing the survival of HNSCC cells." (PMID 37760543, 2023). "The increased IL-6 levels during RT could be attributed to a local inflammatory reaction, a response by the immune system to RT, or the release of IL-6 due to the destruction of tumor cells." (PMID 37373957, 2023). "MerTK CAR M reduces tumor burden, increases median survival time, and creates an inflammatory environment by increasing the levels of proinflammatory cytokines in serum, such as IL-β, IL-6, TNF-α, and monocyte chemotactic protein (MCP)-1 In-vivo." (PMID 38017494, 2023). "The observed reduction in tumor burden and tumor size in TG mice was associated with decreased expression of inflammatory cytokines such as Il-1b, Il-6, Il-17, and Ccl2 in the tumor and tumor-adjacent tissue, as well as a likely reduction in tumor-infiltrating immune cells." (PMID 38090485, 2023). "We have previously shown that IL-6 is produced by the tumor, as well as by pleural macrophages." (PMID 37063842, 2023). "Previously, we reported that CAFs might induce tumor immunosuppression via interleukin-6 (IL-6) and promote tumor progression by blocking local IL-6 in the tumor microenvironment with neutralizing antibody." (PMID 36764954, 2023). "In addition, high expression of IL-6 and low expression of p21 were found in PCa tumor tissues of primary PCa tumor-bearing mice with obese." (PMID 37170248, 2023). "For example, IL-6 has been reported to facilitate tumor invasion by disrupting cell adhesion." (PMID 36675039, 2023). "They argued that high expression of PLCG2 might help form anti-tumor TME via IL-6/JAK/STAT3 signaling pathway, and then promote the proliferation, invasion and metastasis of tumor cells." (PMID 37074454, 2023). "Interestingly, elevated serum IL6 and TNF levels were found associated with tumor recurrence in NSCLC patients." (PMID 37085672, 2023). "In the future, it may be necessary to consider novel markers such as NLR and IL-6, in addition to tumor markers in atezo/bev therapy." (PMID 37296889, 2023). "Since our results demonstrated that IL-10 and IL-6 cytokines levels are crucial in defining the antitumoral action of mifamurtide, we first assayed cell viability of OS tumor cells treated with mifamurtide in the presence or absence of anti-IL-10 and anti-IL-6 blocking antibodies." (PMID 37835437, 2023). "In contrast, the IL‐6 mediated signalling pathways were enriched in the tumour edge." (PMID 37491740, 2023).
tumor (continued). "Furthermore, CAF can reduce CD8+ T cell recruitment and inhibit their cytotoxic activity against tumor cells by releasing IL-6 and TGF-β." (PMID 37007004, 2023). "Indeed, literature data suggested that the STAT3 pathway is activated upon tumour cell stimulation with IL-6." (PMID 36979673, 2023). "The outcomes of their investigation revealed promising effects, including the mitigation of tumor-induced elevation of muscle IL-6 transcript levels and downregulation of Bcl-2/adenovirus E1B 19-kDa-interacting protein (BNIP3), a marker associated with mitophagy." (PMID 37755304, 2023). "A few studies demonstrated that the expression of IL-6, IL-8, and IL-1β could promote the tumor relapse and metastasis." (PMID 37437020, 2023). "On the other hand, HMGB1 produced by the tumor-specific macrophages can regulate the microenvironment through IL-6/STAT3/(programmed death-ligand 1) PD-L1 pathway and IL-6/NF-κB/(matrix metalloproteinase 9) MMP-9 pathway leading to further immunosuppression and aggressive phenotypes of OSCC cells." (PMID 37511951, 2023). "IL-6 and IL-8, known SASP-associated factors, mediate the protumorigenic effects of senescent cells because they establish a chronic inflammatory TME that triggers tumor growth." (PMID 36945046, 2023). "In addition, IL-6 secreted by MSCs can promote tumor progression by activating JAK2/STAT3 signaling and upregulating NF-κB." (PMID 37666813, 2023). "However, only CISP resulted in the strongest increase of CD8 T cells, NK cells, M1 macrophage and anti-tumor cytokines including IL-6, IFNγ, IFNβ, TNFα and IFNα in LLC tumors." (PMID 37607938, 2023). "In addition, pro-inflammatory cytokines, especially TNF and IL-6, are critical tumor promotors that trigger the development of CACs." (PMID 37275854, 2023). "Our results showed elevated plasma levels of FGF, IL-6, IL-8, M-CSF, VEGF, TNF-alpha, and IL-17a, molecules previously associated with larger tumor size, metastasis, and poor prognosis, as well as persistent HPV infection in older women with evidence of an immune deficit." (PMID 38114557, 2023). "Our analysis of correlations between FOX gene expression and IL-1α or IL6 revealed 10 members that might be involved in tumor senescence." (PMID 36622275, 2023). "Furthermore, the Fc-VFD inhibits the secretion of proangiogenic factors, VEGF-A and IL-6, from cancer and macrophage cells in the tumor microenvironment (TME)." (PMID 35895109, 2023). "For instance, inflammatory cytokines produced by tumor cells, such as tumor necrosis factor‐α and interleukin 6, are thought to contribute to muscle wasting and atrophy by inducing oxidative stress in skeletal muscles and activating muscle degradation pathways." (PMID 37927935, 2023). "Thus, loss of Kindlin-1 impacts several immune cell types that are known to contribute to anti-tumor immunity and future studies will explore how other factors act in concert with IL-6 to drive anti-tumor immunity in response to Kindlin-1 depletion." (PMID 36883731, 2023). "Therefore, it is reasonable to expect that in addition to IL-6, tumor derived exosomes alter their gene expression to promote the adipose tissue browning observed in CC." (PMID 36672227, 2023). "Multiple cytokines (such as VEGF, PDGF, IL-6) secreted by platelets contribute to the formation of an immunosuppressive tumor microenvironment and can reduce the ability of NK cells to recognize tumor cells." (PMID 37477536, 2023). "In addition, SFI reduced the levels of proinflammatory cytokines IL-2, IFN-γ, and TNF-α in spleen, However, the mRNA levels of IL-2, IFN-γ and TNF-α in tumor tissues were significantly increased, while IL-6 mRNA levels were significantly decreased." (PMID 37355637, 2023). "Indeed, we found that tumor growth was significantly reduced in mice treated with combined IL-6– and CTLA‐4–blocking Abs compared with mice treated with isotype control Abs (P = 0.0001), single-agent CTLA-4 blockade (P = 0.0207), or IL-6 blockade (P = 0.0002)." (PMID 36881480, 2023).
tumor (continued). "Tumor-growth factor (TGF) and platelet-derived growth factor (PDGF) induce the transformation of tumor fibroblasts (FHNR) in cancer-associated fibroblasts (CAFs), which play a key role in tumor progression, producing pro-tumoral cytokines (e.g., IL-6, IL-8, TNF, IL-10)." (PMID 37842234, 2023). "The activated p38 MAPK, in turn, promotes the production of cytokines (TGFβ and TNFα) and interleukins (IL-6, IL-8, and IL-1β) within the tumor microenvironment, all of which are known to play a role in promoting tumor growth, angiogenesis, invasion, and metastasis." (PMID 36993955, 2023). "Furthermore, STAT3 regulates the synthesis of IL-6, and IL-6 is also released by the immune cells in the tumor microenvironment." (PMID 37176160, 2023). "Consequently, CAFs including Hp-AGFs mediate cancer-related inflammation by secreting numerous pro-inflammatory and tumor promoting factors including IL-6, IL-8, SDF-1, TGF-β, EGF, and HGF." (PMID 37460910, 2023). "In addition, the activation of the NF-κB/IL-6 pathway in response to INK4a/ARF inhibition triggering tumor growth and development has been described recently." (PMID 37550793, 2023). "Infiltrated immune cells shift their phenotypes from anti-tumor, also known as pro-inflammatory phenotypes, to pro-tumor phenotypes because tumor cells increase interleukins and chemokines such as IL-2, IL-4, IL-6, IL-7, IL-10, IL-12, and CXCL12 concentrations." (PMID 37533070, 2023). "For example, tumor-derived IL6 inhibits the activity and function of NK cells." (PMID 37570749, 2023). "Recent studies have reported that CAFs can sense tumor cell genomic stress by expressing interferon (IFN)-β1, which leads to the increased production of associated factors such as CXC ligand 1 (CXCL1) and CXC ligand 10 (CXCL10), IL-6, IL-8, and IL-11." (PMID 37173977, 2023). "Concomitant with increased tumor incidence, RO mice displayed an approximately 2-fold higher abundance of proliferative cells in the colon and a significantly higher abundance of colonic IL-6, IL-1β and Tnf-α compared to RY mice." (PMID 38031252, 2023). "For example, increased levels of the adipocyte‐related hormone, resistin, the pro‐inflammatory cytokine, IL‐6, and the CC chemokine, CCL2, within the TME of AA women gives rise to an increased density of M2 macrophages, also known as tumor‐associated macrophages." (PMID 36632988, 2023). "Furthermore, BBR suppresses migration and invasion of tumor cells via the IL-6/JAK2/STAT3 signaling pathway and inhibiting MMP-9 protein levels." (PMID 37371856, 2023). "NF-κB and IL-6/STAT3 signalings are important regulators in tumor inflammation." (PMID 37781036, 2023). "IL-6 is another cytokine that promotes cancer progression by up-regulating different pathways that involve apoptosis, angiogenesis, invasiveness, metastasis, or tumor cell metabolism, among others." (PMID 38239364, 2023). "By activating the IL-6-Stat3 signaling pathway, IL-17 can accelerate tumor growth." (PMID 37764733, 2023). "Galectin-4 was proposed as a tumor suppressor inhibiting cell proliferation by down-regulating wingless/integrated (Wnt) and IL-6/NF-κB/Signal transducer and activator of transcription 3 (STAT3) signaling that balance epithelial cell homeostasis in the intestine." (PMID 36873388, 2023). "IL-6 signals inhibit several immunocompetent cell activation in the tumor microenvironment." (PMID 37081512, 2023). "In addition, the MDSCs produced inhibitory enzymes through the IL-6 signaling pathway to reduce effector T-cell immunity and promote tumor progression within the tumor microenvironment." (PMID 37296628, 2023). "With a transwell assay we showed that IL-6 neutralizing antibodies could prevent the invasion and migration of LLCs cultured with CM from TaglnOE iMEFs, and suppress the number of tumor spheres in LLCs." (PMID 36990991, 2023).
tumor (continued). "The overall effect is to promote tumor progression, as M1-like macrophages could cascade a stem-like phenotype of tumor cells via the IL6/Stat3/THBS1 feedback loop." (PMID 36614179, 2023). "Interleukin-6 (IL-6) is an important trigger of tumor-promoting inflammation." (PMID 36891151, 2023). "Tumor-associated micro environmental interferon (IFN) interacts to the interferon receptor expressed on TAM, triggering the JAK-STAT signaling cascade and leading to the production of several pro-inflammatory cytokines (IL-1, IL-6, and NOS2)." (PMID 37138860, 2023). "Moreover, IL-6 increased hypoxia-inducible factor 1α (HIF1α) expression and induced tumor immunosuppression by enhancing glucose uptake by cancer cells and competing for glucose with immune cells." (PMID 36764954, 2023). "SOCS1 may bind to the JAK2 kinase SH2 domain, inhibiting its activity, and is also a negative regulator of IL-6; therefore, it may function as a tumor suppressor in multiple myeloma." (PMID 37514090, 2023). "Lin28B increased IL-6 and IL-10 production, which could convert infiltrated neutrophils from tumor-suppressive to tumor-promoting." (PMID 37496019, 2023). "Moreover, the authors showed that the survival of tumor cells detached from the extracellular matrix tumor cells, which would normally undergo apoptosis (anoikis), is IL-6-dependent and acts in an autocrine fashion." (PMID 37685940, 2023). "Furthermore, this expression is also induced on immune cells as a result of chronic stimulation and the cytokine environment (IL-4, TGF-β, and IL-6) in the tumor microenvironment." (PMID 37567938, 2023). "The IL-6 secreted by activated fibroblasts enhanced tumor-cell proliferation and chemoresistance." (PMID 37173963, 2023). "Moreover, tumour‐secreted cytokines such as IL‐6, IL‐1, IL‐11, LIF can have systemic effects that lead to anorexia, systemic metabolic dysfunction, and cachexia." (PMID 37759102, 2023). "Tumor cells were examined by Western blot assay to determine whether IL-6 knockout affects the role of sorafenib in regulating PFKFB3 and HIF-1α." (PMID 37476196, 2023). "Notably, Cluster 1, 2, and 4 showed better response to ICIs, which should be due to TME supporting anti-tumor immunity, including IL6/JAK/STAT3 signaling, tumor necrosis factor (TNFA, TGFB) and interferon (IFNA, IFNG) pathways." (PMID 36817452, 2023). "Additionally, IL-6 has been reported to prevent cellular senescence by increasing telomerase activity, thereby promoting tumor growth." (PMID 38022654, 2023). "Increased CAF markers indicate the acquisition of a malignant phenotype, and functional malignant enhancement of CAF was observed, given the elevation of IL-6, which is known to be produced from CAFs, regulated immunosuppressive tumor-infiltrating lymphocyte population in CAF-rich tumors." (PMID 37296933, 2023). "In PDAC, CAFs with high expression of ISO3/ISO4 can effectively secrete immunosuppressive cytokines (TGF-β1, IL-8, and IL-6) to maintain the characteristics of inflammatory CAFs and produce functional desmoplastic ECMs (d-ECMs) that support tumor cell survival and proliferation." (PMID 37143134, 2023). "IL-6 mediates an increase in tumor cell malignancy, which may be related to its activation of the STAT3 signaling pathway." (PMID 37576403, 2023). "Although previous clinical studies report that CRC patients have significantly enhanced IL6 levels that correlate with tumor size, stage, metastasis and survival rate, the source of the IL6 is unknown." (PMID 37062842, 2023). "Activated tumor infiltrating DCs secrete higher amount of IL-12 and IL-6." (PMID 37122749, 2023). "IL-6 in the tumor microenvironment can regulate the self-renewal and survival of breast CSCs." (PMID 37924094, 2023). "For example, NFs were induced by HPV-negative oropharyngeal cells to release hepatocyte growth factor (HGF) and IL-6, which might encourage tumor cell formation by activating c-met and STAT3." (PMID 37055382, 2023).
tumor (continued). "On the other hand, IL-6 and TNFα are the main molecular mediators of the anti-tumor functions of MCs, with the latter able to directly activate either apoptosis or necroptosis pathways in tumor cells." (PMID 37376140, 2023). "Interestingly, IL-6 derived from CAFs-induced upregulated phosphorylation of STAT3 in DCs, a surprising result given the previously similar results reported for IL-6 derived from tumor cells." (PMID 38313431, 2023). "In addition, MDSCs promote epithelial mesenchymal transition by secreting IL-6, which increases angiogenesis and speeds up tumor progression." (PMID 37513975, 2023). "Furthermore, miR-1246 derived from extracellular vesicles of highly metastatic tumor cells induces IL-6 expression, which, in turn, upregulates IL-6 and induces 5-FU resistance through STAT3 and AKT activation in endothelial cells." (PMID 38069225, 2023). "For instance, a prominent Th1/Th2 phenotype shift, expansion of myeloid-derived suppressor cells (MDSC), tumor-associated macrophages (TAMs), decreased CD8+ T cells, along with increased representation of certain inflammatory mediators such as IL-6, IL-17 contribute to tumor advancement." (PMID 38074634, 2023). "Antibody-mediated bridging between FcγRIIIA/FcγRIIA on NK cells/phagocytes and target antigen on the tumor cells can trigger the release of IFNγ, TNFα, IL6, and MCP-1 during the ADCC reaction and NK cell–secreted IFNγ and TNFα were shown to potentiate the NK-mediated target cell lysis." (PMID 37067909, 2023). "Moreover, stress hormones can cause upregulation of cytokines, i.e., VEGF, TGF, IL6 or IL8, which are proangiogenic and/or favor tumor progression." (PMID 36766760, 2023). "CD10+ GPR77 + CAFs enriched a survival niche for cancer stem cells (CSCs), enhanced tumor formation, and induced cancer chemoresistance by secreting IL-6 leading to driving the activation of NF-κB via p65 phosphorylation and acetylation, which maintained by complement signaling via GPR77." (PMID 37480115, 2023). "Additionally, there was a significant increase in C-reactive protein (CRP), interleukin-6 (IL-6), and various tumor markers, indicating a rapidly deteriorating and urgent situation." (PMID 37916176, 2023). "To determine whether IL-6 has an effect on PCa stemness, we collected both tumor spheres and IL-6-treated sphere pellets." (PMID 37987305, 2023). "Since TME can be changed from tumor-friendly to tumor-suppressive by switching phenotypes from M2 to M1, IL-6-mediated phenotypic transformation of macrophages may serve as a novel therapeutic target in the PROC." (PMID 37124547, 2023). "However, when acting as a paracrine factor, IL-6 promotes angiogenesis, which contributes to tumor progression." (PMID 36945046, 2023). "Moreover, myeloid cells promote tumor growth by secretion of pro-inflammatory cytokines such as IL1b, IL6 and IL15, which have been shown to promote inflammation and tumor growth." (PMID 36761972, 2023). "Furthermore, we observed that MIP treatment significantly increased the production of pro-inflammatory cytokines IL-12 and IL-6 from tumor infiltrating DCs in a type 1 IFN dependent pathway." (PMID 37122749, 2023). "Moreover, IL-6 and IL-8 expression in the CMGTs positively correlated with the histological grade, whereas, IL-6 expression in the CMGTs positively correlated with tumor metastasis (P < 0.05)." (PMID 36693957, 2023). "The IL-6 may contribute to the hormone release, to tumor growth and proliferation and to the production of angiogenic factors, such as the vascular endothelial growth factor-A (VEGF-A)." (PMID 36658300, 2023). "Conversely, other studies have suggested that IL-10 can enhance the proliferation and activation of CD8+ T cells while suppressing the expression of IFN-g-induced cytokines and specific pro-inflammatory cytokines (IL-12 and IL-6), leading to an anti-tumor effect." (PMID 37910571, 2023).